MTOR (mechanistic target of rapamycin kinase)
Diseases named in the same sentence as MTOR in open-access papers (continued):
Sharing a sentence is not in itself a finding about the gene and the disease.
lymphoma (165 papers, 2009 to 2025). A malignant (clonal) proliferation of B- lymphocytes or T- lymphocytes which involves the lymph nodes, bone marrow and/or extranodal sites. "The IL4 and BCR-induced mTOR activation was reduced by CREBBP mutants and augmented by mutant STAT6, establishing a link between STAT6 mutations and mTOR regulated pro-growth pathways in lymphoma." (PMID 39910284, 2025). "PI3K/Akt/mTOR pathway activation in lymphomas is associated with over-expression of various cytokines and growth factors, such as IL-6, IL-10 and the platelet-derived growth factor (PDGF)." (PMID 37762410, 2023). "Bcl2 is a star protein that inhibits apoptosis, and targeting the PI3K/AKT/mTOR pathway causes downregulation of Bcl2 protein expression, ultimately leading to lymphoma cell death." (PMID 37822596, 2023). "The PI3K/Akt/mTOR signaling pathway plays a critical role in a variety of cellular processes, such as cell proliferation and survival, and in lymphomas it is associated with the over-expression of various cytokines and growth factors in malignant lymphomas." (PMID 37762410, 2023). "This is the first comparative omics study in human lymphoma reporting down-regulation of the PI3K/mTOR pathway associated with decreased translation, in accordance to our previous study in MCL." (PMID 37568720, 2023). "Direct inhibition of glycolysis with 2-deoxy-d-glucose (2-DG) reduced the production of lactate, similar results were observed with the inhibition of mTOR or HIF1α, and all three treatments were toxic to PD-1-deficient lymphoma cells." (PMID 37723306, 2023). "The loss of IL-6 in MYC lymphomas also leads to a compensatory increase in proteins expressed in the mTOR pathway." (PMID 33651821, 2021). "Aberrant activation of the PI3K/Akt/mTOR pathway is a hallmark of lymphomas, including Hodgkin lymphoma (HL) and non-Hodgkin lymphomas (NHLs)." (PMID 33489922, 2020). "It has been indicated that the MYC-driven lymphoma is associated with mTOR activation and an endogenous DNA damage response transduced by PI3K-related kinase." (PMID 24252186, 2013). "Among aberrantly activated signaling cascades that are implicated in the pathogenesis of lymphomas is the mammalian target of rapamycin (mTOR) pathway, which is involved in many vital cellular processes." (PMID 21822434, 2012). "Resistance to doxorubicin (Dxr) or cyclophosphamide in myr-AKT activated or PTEN+/−Eμ-Myc lymphomas has been linked to (a) defective apoptotic program(s) dependent on increased mTOR activity and linked to elevated translation initiation rates." (PMID 19412536, 2009). "Moreover, there was a strong rationale for mTOR inhibitors (mTORi) effects in many hematological diseases due to the associated hyperactivation of mTOR, as in acute leukemia, lymphoma, multiple myeloma, Waldenström macroglobulinemia, and GVHD." (PMID 37437037, 2023). "Consistent with this possibility, rapamycin administration in human lymphoma cells alters gene expression in a manner similar to that observed upon starvation and decreased mTOR signaling has been linked to starvation-induced stress, higher mitochondrial respiration and extended life-span in yeast." (PMID 22412899, 2012). "Taken together, these findings confirm our CRISPR screen results and demonstrate that 2-day mTOR inhibition unexpectedly enhances immune response gene expression in both lymphoma and primary B cells." (PMID 41026602, 2025). "Canine and human lymphomas share molecular mechanisms, including the activation of key pathways like NF-κB and mTOR, and genetic and epigenetic alterations." (PMID 40002191, 2025). "Studies have shown that GSK-3β is directly involved in cell death induced by PI3K/mTOR inhibitors and panhistone deacetylase inhibitors in lymphoma cell lines." (PMID 40643495, 2025).
lymphoma (continued). "Through transcriptomic analysis, the research identifies over 2,300 differentially expressed genes and highlights the disruption of critical signaling pathways like B-cell receptor signaling and mTOR, essential in lymphoma development." (PMID 41170526, 2025). "Prolactin has been shown to activate the PI3K/Akt/mTOR pathway in a dose‐ and time‐dependent manner in lymphoma models." (PMID 41322031, 2025). "Sertraline also disrupts protein synthesis and survival pathways, with mTOR inhibition and impaired translation initiation noted in breast and lymphoma models." (PMID 40874450, 2025). "Our studies have contributed to the characterization of mTORC1 activity in hematological malignancies and even to the investigation of both mTOR complexes in leukemias and lymphomas." (PMID 38515456, 2024). "The exception appears to be lymphoma lines, which shut off mTOR activity following CDK4/6 inhibition, thus preventing overgrowth and mitochondrial scaling." (PMID 38438376, 2024). "The PI3K/AKT/mTOR signaling pathway plays a significant role in B-cell growth and development, and in lymphomas, this pathway exhibits heightened activity." (PMID 38381215, 2024). "We found that the main signaling pathway of this gene is PI3K / AKT / mTOR, and the activation of this pathway is also the main driving force for poor prognosis in lymphoma." (PMID 39054516, 2024). "The mTOR pathway also acts as a bypass pathway of resistance and some investigators have shown a synergistic effect of combining ALK inhibitors with mTOR inhibitors in lymphoma cells." (PMID 37773318, 2023). "Bimiralisib (PQR309), an oral, novel, selective dual PI3K/mTOR inhibitor, had anti-lymphoma activity as a single agent or in combination with ibrutinib, lenalidomide, and rituximab in vitro." (PMID 36982568, 2023). "Lymphomas resistant to proteasome inhibitors show increased expression in BCR and activation of the BCR signaling pathway enhances the activity of SFK, especially LYN, and downstream kinases PI3K/AKT/mTOR in proteasome inhibitor-resistant lymphoma cells." (PMID 36765939, 2023). "To test the dependency of fully transformed lymphomas with Pdcd1 deletion on the released mTOR–HIF1α–glycolysis cascade, we incubated ITK–SYK+PD-1− cells with small-molecule inhibitors of mTOR, HIF1α or glycolysis." (PMID 37723306, 2023). "The long-lived and highly proliferating lymphoma B-cells are favored by excessive mTOR pathway activation, which is correlated to poor prognosis in NHL and B-cell acute lymphoblastic leukemia (LAL-B) patients." (PMID 37176092, 2023). "Others have shown in multiple disease models, including small cell lung cancer and lymphoma, that navitoclax in combination with mTOR inhibitors is efficacious." (PMID 37210412, 2023). "Among the novel N3a-sensitive PI3K/mTOR-reducing proteins in lymphomas, were increased PHLDA3 (R_cHL/MCL), OSMR (R_cHL), COL6A3, and Rictor (P_ALCL/cHL)." (PMID 37568720, 2023). "Taken together, these results indicate that the simultaneous pharmacological inhibition of PI3Kβ/δ and mTOR has a broad and profound anti-lymphoma activity and is able to abolish DLBCL tumor growth in vivo." (PMID 36352190, 2023). "Gary J.M. and colleagues observed the existence of an mTOR-let7a/miR-21/CDK 6 axis in thymic T-cell acute lymphoblastic leukemia/lymphoma (T-ALL/LBL)." (PMID 36498861, 2022). "Mammalian target of rapamycin (mTOR) signaling, a target relevant for MM tumorigenesis, was found to be inhibited in human lymphoma xenograft models by chronic low dose ethanol." (PMID 35846225, 2022).
lymphoma (continued). "The activation of the PI3K/protein kinase B (AKT)/mammalian target of the rapamycin (mTOR) pathway also plays a key role in lymphoma, and many signaling pathway inhibitors have been developed to treat FL, DLBCL, MCL, small lymphocytic, and T-cell NHL." (PMID 36555171, 2022). "Several FDA-approved small-molecule inhibitors such as idelalisib, copanlisib, and duvelisib targeting the PI3K/Akt/mTOR pathway are currently in clinical development at various stages for the treatment of lymphoma." (PMID 36235333, 2022). "Rapamycin reverses the chemoresistance in AKT-overexpressing lymphomas in a murine lymphoma model via disruption of the AKT/mTOR/eIF4E signaling pathway by inhibiting mTOR activity." (PMID 35111368, 2022). "Identifying the contribution of mTOR activity in cyclin D1 overexpression in mantle cell lymphomas highlighted the possible use of mTOR inhibitors (mTORIs) in lymphomas and other malignancies." (PMID 35029792, 2021). "A similar expression pattern of the Akt/mTOR pathway was observed in all pSS patient subgroups, independently from the risk of developing NHL or having lymphoma." (PMID 34948236, 2021). "The pharmacological inhibition of mTOR through rapamycin and its derivatives (rapalogs) has been approved for various treatments, including cancers, and studied in the context of lymphomas." (PMID 34221985, 2021). "This analysis shows that tumor models with high mTOR activity corresponded to greater tumor growth inhibition with zotatifin treatment, a dependence that was also observed for zotatifin in a panel of lymphoma models." (PMID 34900714, 2021). "OSS_128167, a novel targeted inhibitor of Sirt6, exerted excellent anti-lymphoma effects via inhibiting PI3K/Akt/mTOR signaling." (PMID 32711549, 2020). "In this review, we summarize the literature on dual PI3K/mTOR inhibitors focusing on the lymphoma setting, presenting both the three compounds still in clinical development and those with a clinical program stopped or put on hold." (PMID 32033478, 2020). "Next, to validate downregulation of the PI3K/AKT/mTOR pathway in Eμ-Myc lymphomas upon PRDM15 depletion, we starved WT and KO cells overnight and subsequently stimulated them with insulin and IGF1." (PMID 32665551, 2020). "Treatment of lymphoma cells with cholesterol synthesis inhibitors in combination with Akt/mTOR inhibitors was also examined." (PMID 32985581, 2020). "There are plenty of preclinical data sustaining the anti-tumor activity of dual PI3K/mTOR inhibitors as single agents and in combination in lymphomas." (PMID 32033478, 2020). "The phosphatidylinositol 3-kinase (PI3K)/AKT/mammalian target of rapamycin (mTOR) signaling cascade is an important therapeutic target for lymphomas." (PMID 31167506, 2019). "With PEL being among the most mTOR-addicted lymphomas, the low IC50 for MLN0128 is consistent with primary inhibition of only mTOR kinase." (PMID 30782662, 2019). "This agent extended survival when combined with chemotherapy in both the Eμ-MYC/eIF4E and Eμ-MYC/PTEN+/− lymphoma models, in which MYC and mTOR are deregulated to drive lymphoma onset." (PMID 29799508, 2018). "c-MYC- and PI3K/mTOR-inhibitors decreased viability of the lymphoma cells and led to decreased glucose uptake, expression of glycolysis-associated genes, and glucose metabolism-regulating miRNAs." (PMID 28724379, 2017). "Activation of mTOR induces cell growth and survival in cancer, and especially in lymphoma, Myc activity is known to depend on the mTOR pathway." (PMID 29259783, 2017).
lymphoma (continued). "In vitro analysis indicated that low 4EBP1 expression and/or high eIF4E expression by lymphoma cells conferred resistance to mTOR inhibitors, explaining the poor therapeutic efficacy against MCL." (PMID 27119356, 2016). "In clinical trials, treatment with a pan-isoform PI3K and mTOR inhibitor SAR245409 (XL765) for relapse/refractory lymphoma produced partial remission." (PMID 27119356, 2016). "To evaluate the effects of BKM120 and BEZ235 on PI3K/AKT/mTOR signaling, we analyzed the phosphorylation status of Akt and some downstream targets (including mTOR, 4EBP1, and p70S6kinase) in lymphoma cell lines treated for 24 h with the IC50 of these drugs." (PMID 26557706, 2015). "High levels of Mcl-1 and Bcl-XL have been reported to be a mechanism of both de novo and acquired resistance to ABT-199 in lymphoma cell lines, which is overcome by the addition of mTOR inhibitors, and possibly with acadesine." (PMID 26110568, 2015). "Since transcription was unaffected, a polysome analysis in lymphoma cell lines was carried out in order to explore the mechanism through which this dual mTOR inhibitor suppresses translation." (PMID 25839159, 2015). "Promising preclinical and clinical data support the rationale for therapeutic use of PI3K/Akt/mTOR inhibitors in lymphoma treatment and, crucially, these inhibitors are well tolerated." (PMID 26557706, 2015). "Supporting this, other compounds that target mTOR pathway were also described to inhibit Mcl-1 at a translational level in lymphomas." (PMID 26110568, 2015). "Upregulation of the PI3K/Akt/mTOR pathway occurs in many human cancers, including lymphoma; therefore, this pathway is considered a target for anticancer therapy in several human cancer types." (PMID 25669976, 2015). "This article discusses the dysregulation of PI3K/mTOR signaling in hematologic malignancies, including acute and chronic leukemias, lymphomas, and lymphoproliferative disorders." (PMID 24904824, 2014). "One of them was Everolimus, a mTOR inhibitor, used as a single-agent in elderly, heavily pretreated patients affected by aggressive lymphomas." (PMID 25045615, 2014). "Bhatt and Damania consider the roles of PI3K and mTOR in the transformation of B cells by Kaposi sarcoma viruses and how PI3K and/or mTOR inhibitors should be considered for the treatment of virally induced lymphomas." (PMID 25404931, 2014). "The majority of B-cell lymphomas also have been found to have constitutive activation of the PI3K/mTOR pathway, and MTIs have shown anti-lymphoma activity both in vivo and in vitro." (PMID 24904824, 2014). "Mammalian target of rapamycin (MTOR) signaling plays a major role in tumor cell growth and is aberrantly activated in lymphoma." (PMID 23866964, 2013). "As PI3K/Akt/mTOR pathway plays a key role in the proliferation and survival of lymphoma cell, various inhibitors targeting this pathway have been studied in different types of NHL." (PMID 24252186, 2013). "Based on in vitro activity of mTOR inhibitors in numerous lymphoma cell lines, both everolimus and temsirolimus have completed phase II clinical trials in NHL." (PMID 21092307, 2010). "This review will discuss the rationale for and summarize the reported findings of initial and ongoing investigations of mTOR inhibitors and other small molecule targeted therapies in the treatment of lymphoma." (PMID 21092307, 2010). "Ridaforolimus and sirolimus are other mTOR inhibitors that also are in clinical testing for the treatment of lymphomas." (PMID 21092307, 2010).
lymphoma (continued). "For these studies, we used mice bearing Pten+/−Eμ-Myc lymphomas since mTOR is activated in these tumors and they respond to the combination of Dxr and Rap treatment, as well as to combinations of Dxr and the translation initiation inhibitor, silvestrol." (PMID 19412536, 2009). "The molecular docking and MMGBSA analysis of the compound DMBP against a panel of lymphoma-associated protein targets—AKT1, HSP90AA1, MTOR, MAPK1, and MDM2—revealed distinct binding affinities and interaction profiles, indicative of its potential as a multi-target therapeutic agent." (PMID 40699833, 2025). "It is hypothesized that metformin may inhibit lymphoma cell oxidative metabolism or mTOR signaling, as DLBCL cells often have high PI3K/mTOR activity, enhancing chemo-induced apoptosis." (PMID 41050082, 2025). "MTOR signalingpathway is well known to play a key role in the development of lymphomas." (PMID 40896706, 2025). "Additionally, research in lymphoma suggests that inhibiting mTOR can downregulate JunB protein levels and reduce cell proliferation, indicating that JunB is a crucial target of mTOR." (PMID 40918148, 2025). "Thus, we here addressed cellular responses to therapeutic inhibition of Pim kinases and identified a PI3K/Akt‐driven activation of mTOR as a significant escape mechanism mitigating the anti‐lymphoma effects of Pim inhibition." (PMID 40165380, 2025). "The lack of growth in the three lymphoma lines was associated with reduced mTOR activity during the G1 arrest and a lack of mitochrondrial scaling." (PMID 38438376, 2024). "In addition to in vitro lymphoma models, mTOR hyperactivity has been characterized in the most common solid tumors and several human malignant tissues." (PMID 38515456, 2024). "Moreover, the increased sensitivity of C23 upon MYC expression was alleviated by the mTOR inhibitor Rapamycin in two independent murine lymphoma cell lines." (PMID 39341827, 2024). "Third-generation mTOR inhibitors (e.g., RapaLink-1) are also being developed for the treatment of various advanced cancers (e.g., renal, breast, mantle cell, and other high-grade lymphomas)." (PMID 38515456, 2024). "As MCL and other indolent lymphomas remain incurable, mTOR inhibitors, especially temsirolimus, might be further tested in combination with other agents in the future." (PMID 37762410, 2023). "Moreover, treatment of ITK–SYK+PD-1− lymphoma-bearing mice with the mTOR inhibitor torin-1, which blocks mTOR activity within tumor cells in vivo, significantly prolonged survival (P = 0.0057)." (PMID 37723306, 2023). "AMPK activation could block lymphoma cell growth via inhibition of the mTOR pathway and the induction of autophagy." (PMID 36982568, 2023). "Since mTOR is a negative regulator of autophagy and our findings showed N3a-induced down-regulation of the mTOR pathway, autophagy induction in N3a-treated lymphoma cells may be mediated, partly via down-regulated PI3K/mTOR pathway." (PMID 37568720, 2023). "As RRAGC mutation results in hyperactivation of mTOR, targeting mTOR could be a therapeutic strategy for RRAGC-mutant lymphoma." (PMID 37749558, 2023). "The combined immunosuppressive and potential anti-lymphoma effects by mTOR inhibitors (i.e. Sirolimus, Everolimus) are hypothesized, but not systematically validated, rationales." (PMID 37427100, 2023).